PDPN (podoplanin)
Diseases named in the same sentence as PDPN in open-access papers (continued):
Sharing a sentence is not in itself a finding about the gene and the disease.
tumor (continued). "It has been proved that podoplanin has an influence on tumor-associated lymphangiogenesis and activation of cancer-associated fibroblasts (CAFs)." (PMID 34566887, 2021). "In a subset of tumour‐associated macrophages (TAMs), the highest expression of podoplanin (PDPN) is found." (PMID 34632719, 2021). "The multimerization of Clec-2 increases the affinity for podoplanin and in turn causes podoplanin clustering, resulting in a strong interaction between platelets and tumor cells." (PMID 33937274, 2021). "Intriguingly, high CALB2 or PDPN expression was strongly associated with a poor clinical outcome, and calretinin expression was observed at the invasive tumor edges of HGSC metastases." (PMID 32533757, 2020). "The effects of PDPN deficiency on the tumor invasive ability were assessed using 8-μm membrane trans-well chambers." (PMID 32581653, 2020). "PDPN expression on cancer-associated fibroblasts (CAFs) is regulated by inflammatory cytokines within tumors and is associated with enhanced tumor invasion and has emerged as a target for cancer therapy." (PMID 36304708, 2020). "Taken together, these results partially recapitulate the associations of DDR1 and PDPN with ALI detected in OSCC tumor tissues." (PMID 32244515, 2020). "In a breast carcinoma xenograft animal model, podoplanin overexpression promoted tumor-associated lymphangiogenesis, invasiveness and lymph node metastasis." (PMID 32599908, 2020). "Some reports demonstrated that PDPN is associated with tumor malignancy through the promotion of tumor cell invasion and distant metastasis with or without platelet aggregation." (PMID 32380790, 2020). "Nevertheless, underlying mechanisms of PDPN in tumor cell invasive ability as well as EMT induction, especially by platelets, are still not fully understood." (PMID 32581653, 2020). "PDPN is known to be linked with several aspects of tumor malignancies in certain types of human and canine tumors." (PMID 33238582, 2020). "On the other hand, it has been demonstrated that tumour expression of PDPN in head and neck SCC (HNSCC) is associated with advanced forms of the disease, metastases in regional lymph nodes, and low survival." (PMID 31967978, 2020). "CCL21 is also a potent chemoattractant in the tumor microenvironment, and its binding to podoplanin-expressing cancer-associated fibroblasts (CAFs) is involved in tumor immune escape." (PMID 30736372, 2019). "Recent studies suggested that the role of PDPN is associated with tumor metastasis, malignancy, and poor prognosis." (PMID 31208371, 2019). "Podoplanin also increases activity of Rho family GTPases, which also have been linked to tumour cell motility." (PMID 31452946, 2019). "We observed an increase in the fluorescence intensity of PD-L1 on CD45-Epcam-CD31+PDPN + tumor associated LECs, which we also observed with implantation of E0771 tumors into BL6 mice." (PMID 31244852, 2019). "Here, IDO expression was predominantly observed in mature (CD31+/CD34+/α-sma+) tumor-associated blood vessels and in two patients in lymphatic (podoplanin-positive) vessels." (PMID 30050535, 2018). "For example, PDPN was shown to induce extracellular matrix degradation and tumor invasion in association with MT1-MMP and Rho GTPases in OSCC." (PMID 30002682, 2018). "Podoplanin is a transmembrane glycoprotein and its overexpression has been associated with enhanced cancer cell motility, tumor invasion and poor patient prognosis in head and neck tumors." (PMID 29310601, 2018). "Interference with podoplanin-induced platelet aggregation and activation is directly associated with inhibition of podoplanin-mediated tumor metastasis." (PMID 30279963, 2018). "Cancer-associated fibroblasts express podoplanin, a protein known to cause activation and aggregation of platelets, referred to as tumour-cell-induced platelet activation, through the C-type lectin receptor 2 (CLEC-2)." (PMID 30314362, 2018).
tumor (continued). "The likelihood ratio obtained after Cox regression analysis shows that a 1% increase of PD-L1+ PDPN+ tumor cells will increase the risk of dying with a factor of 1.10." (PMID 29163783, 2017). "Not only in tumor cells themselves but also in cancer-associated fibroblasts (CAFs), podoplanin expression is observed and correlated with tumor malignancy and poor prognosis in lung, breast, pancreatic, and liver cancer." (PMID 28674748, 2017). "In many (12/29) IDC cases, high expression of podoplanin in peripheral stroma was associated with high expression of podoplanin in the tumor stroma." (PMID 28938000, 2017). "On a molecular level, CD9 is known to inhibit integrin-mediated motility and associate with the platelet aggregation-inducting factor podoplanin, thereby preventing platelet aggregation and, consequently, a tumor-cell protective microenvironment." (PMID 27572323, 2016). "Given that PDPN is a important membrane protein associated with metastasis and expressed in tumor cells, treatment targeting PDPN is an attractive therapeutic strategy for the treatment of LNM." (PMID 27351128, 2016). "It was recently reported that podoplanin expression in tumor cells is associated with tumorigenesis in OSCC." (PMID 26622791, 2015). "The expression of podoplanin on the cell membrane was positively correlated with tumor status, venous invasion and UICC stage, and was associated with a poor prognosis in ESCC." (PMID 26095281, 2015). "Membrane expression of podoplanin was significantly associated with tumor status (P=0.001), venous invasion (P=0.035) and Union for International Cancer Control stage (P=0.029)." (PMID 26095281, 2015). "PDPN is associated with malignant progression, tumor metastasis, and poor prognosis in several types of cancer." (PMID 26416352, 2015). "PDPN is also located on lymphatic endothelial cells and cancer associated fibroblasts which can augment tumor invasion and metastasis." (PMID 25826087, 2015). "The interaction between CLEC-2 and Podoplanin has been associated with tumor cell arrest and extravasation (7, 59, –, 61)." (PMID 25368330, 2014). "Given that it is a specific marker of lymphatic vessels, and that increased lymphangiogenesis is often correlated with poor prognosis in cancer patients, the numbers of PDPN+ vessels in a tumor is often used as a diagnostic marker." (PMID 22988448, 2012). "In this study, we have shown that the tumour-associated proinvasive glycoprotein podoplanin is highly expressed in synovial lining layer cells in RA but is rarely found in OA synovial specimens." (PMID 21385358, 2011). "These histological findings suggest that podoplanin in LSCCs contributed to the inhibition of tumor-associated lymphangiogenesis." (PMID 21034514, 2010). "Importantly, in a separate independent cohort of 20 CRC patients, we found that high expression of PDPN was associated with tumor size." (PMID 40842027, 2025). "In tumor cells, PDPN expression is generally linked to poor prognosis." (PMID 40842027, 2025). "Interestingly, the decreased EMILIN-1 levels in tumor tissue associated with the presence of morphologically aberrant podoplanin-positive LVs." (PMID 38941035, 2024). "Therefore, PDPN in tumors and CAFs has been recognized as a useful diagnostic marker and an attractive target for tumor therapy." (PMID 39594582, 2024). "Podoplanin is commonly associated with tumor invasion and metastasis." (PMID 38504986, 2024). "Hence, this study was performed to evaluate the role of PDPN as a potential biomarker in predicting the risk of the malignant potential of OLs as well as the tumor progression in OSCCs." (PMID 37273383, 2023). "Furthermore, PDPN-positive cancer-associated fibroblasts mediate an immunosuppressive tumor microenvironment, which reduces antitumor immunity." (PMID 37894446, 2023).
tumor (continued). "In particular, expression of DKK3 and PDPN was markedly increased in stroma-proximal regions and both are established markers of cancer-associated fibroblasts implicated in support of tumor growth." (PMID 37350578, 2023). "Moreover, PDPN is strongly expressed by LECs and widely present in tumor-associated cells, e.g., in TAMs." (PMID 36671802, 2023). "Furthermore, PDPN is also expressed in cancer-associated fibroblasts (CAFs), a major component of the tumor microenvironment (TME)." (PMID 37894446, 2023). "In addition, PDPN is also expressed in tumor stroma, including cancer-associated fibroblasts (CAFs)." (PMID 36937386, 2023). "Podoplanin may be a promising target protein for developing anti-metastatic drugs, as the Clec-2/podoplanin interaction causes platelet aggregation in the bloodstream, thereby promoting hematogenous tumor metastasis." (PMID 37386100, 2023). "Importantly, Bieniasz-Krzywiec and colleagues found PDPN-expressing macrophages in 4T1 breast cancer-associated cells, which localize in proximity to tumor lymphatics." (PMID 37898403, 2023). "Tumour-like CAFs (tCAFs): We observed strong differential expression of proliferation-, migration- and metastasis-associated genes (e.g., PDPN, MME, TMEM158 and NDRG1) as well as stress-response-associated genes (e.g., ENO1), and GAPDH in a small cluster (n = 786 cells)." (PMID 37463917, 2023). "Moreover, PDPN-positive CAFs are closely associated with the immunosuppressive tumor microenvironment." (PMID 35159384, 2022). "Although associated with poor patient outcomes, the effect of podoplanin expression in CAFs may depend on the type of tumor cells and the tissue from which the CAF originated." (PMID 35936717, 2022). "However, podoplanin was expressed in 45.5% of CAFs and was associated with increased tumor thickness and sentinel lymph node metastasis." (PMID 35163233, 2022). "Importantly, we showed that the combination of periostin‐positive CAFs and podoplanin‐positive CAFs was associated with specific tumor microenvironment features in terms of stromal abundance and immune cell infiltrates." (PMID 36102377, 2022). "Abnormal expression of the PDPN is associated with tumor cell migration and invasion." (PMID 34164422, 2021). "In this context, the aim of this study is to evaluate, through immunohistochemistry, the presence of CAFs and their association with tumour expression of PDPN in biopsies obtained from patients diagnosed with HNC, and to evaluate the association of both with clinicopathological variables." (PMID 31967978, 2020). "In this research we could not demonstrate any significant association between the presence of CAFs and the tumour expression of PDPN." (PMID 31967978, 2020). "Since PDPN is a glycoprotein that causes tumor-specific aberrant glycosylation in tumor cells, a cancer-specific anti-PDPN antibody could specifically recognize cancer-specific aberrant glycosylation." (PMID 33238582, 2020). "Therefore, further studies need to be done in order to unveil the functional role of podoplanin–CD44v association in CSCs and tumor progression." (PMID 33003440, 2020). "Additionally, we further characterize two ECM-associated molecules that were highly overexpressed in HSA tumor tissue, podoplanin (PDPN) and laminin alpha 4 (LAMA4)." (PMID 32571313, 2020). "In addition, podoplanin overexpression in tumor samples from glioma patients was associated with intravascular platelet aggregates and increased risk of VTE." (PMID 31337034, 2019). "However, they observed a worse prognosis and a higher risk for metastases for melanomas with podoplanin positive tumor-associated fibroblasts, suggesting its role as a potential prognostic marker and therapeutic target." (PMID 31934531, 2019). "The expression of podoplanin in tumor cells is associated with cell migration and invasion." (PMID 31508790, 2019). "Therefore, podoplanin was chosen to evaluate tumor-associated lymphangiogenesis in the ICC specimens." (PMID 30849953, 2019).
tumor (continued). "Extent of tumor-associated lymphangiogenesis of ICC was evaluated by quantifying microlymphatic vessel density (MLVD) from immunohistochemical staining of a lymphatic endothelial-specific antibody (podoplanin)." (PMID 30849953, 2019). "Interestingly, Cx43 co-localizes with podoplanin (PDPN), a glycoprotein implicated to have a role in inflammation, in tumor-associated astrocytes." (PMID 29641478, 2018). "Important evidence that PDPN-positive fibroblasts can affect the formation of blood vessels comes from the clinical studies as the presence of large numbers of PDPN-positive CAFs was associated with numerous CD34-positive blood vessels in tumor stroma of IDC samples." (PMID 28938000, 2017). "In addition, it has been shown that low levels of PDPN expression in tumor cells were significantly associated with the presence of lymphatic invasion, lymph node metastasis, and shorter recurrence-free survival, but not with disease-related overall survival." (PMID 27313335, 2016). "Since PDPN expression in tumor cells is associated with increased malignancy, we explored whether PDPN modulates EV biogenesis." (PMID 26893367, 2016). "Likewise, by comparing the proteome profiles of MDCK-CMV and MDCK-PDPN cells, we show in this article that PDPN-induced EMT is associated with a reprogramming of proteins that favors tumor growth, invasiveness and metastasis." (PMID 26893367, 2016). "It was previously shown that premalignant lesions with podoplanin expression at suprabasal layer may truly represent tumor initiating cells and with a higher risk of progression to invasive cancer." (PMID 26558136, 2015). "In addition to cancer cells themselves, PDPN expression in cancer associated fibroblasts has been associated with tumor aggression and poor clinical outcomes." (PMID 25826087, 2015). "Tumours derived from ezrin-deficient cells demonstrated a significant reduction in lymphangiogenesis compared to MDASrc cells, as indicated by lymphatic vessel markers lyve-1 and podoplanin (respectively)." (PMID 25231728, 2014). "While these studies illustrate that PDPN expression in CAFs is linked to poor prognosis for patients, it is important to keep in mind that the effect of PDPN+ CAFs likely depends on the type of tumor cells and the tissue from which the CAFs originate." (PMID 22988448, 2012). "In addition, podoplanin (or aggrus) induces platelet aggregation of tumour cells and has been associated with both EMT-dependent and EMT-independent tumour cell invasion." (PMID 21385358, 2011). "We hypothesized that the reduced potential of lymphogenous metastasis in EBC1-Ps was due to podoplanin-mediated inhibition of tumor-associated lymphangiogenesis." (PMID 21034514, 2010). "A series of these past studies relevant to tumor cell-associated podoplanin suggest its role in promoting cancer progression, especially in enhancing the potential of cancer cell invasion, and this hypothesis has been supported by several past studies." (PMID 21034514, 2010). "Podoplanin expression significantly decreased as T classification increased (P = 0.033) and in consequence there was also a significant inverse association of podoplanin expression with disease stage (P = 0.006), with most stage IV tumours showing low podoplanin expression." (PMID 20196862, 2010). "Podoplanin is a mucin-type sialoglycoprotein that is expressed on a variety of cell types, but not on blood vessel endothelium, and has been implicated in tumor cell-induced platelet aggregation, tumor metastasis and lymphatic vessel formation." (PMID 19025564, 2009). "These processes may influence the expression of tumor-associated biomarkers, including PDPN." (PMID 41594182, 2026). "However, in lung adenocarcinoma and squamous cell carcinoma, Podoplanin-positive CAFs are associated with poor prognosis and may promote tumor invasion and metastasis." (PMID 40094065, 2025).
tumor (continued). "PDPN is a heavily O-glycosylated small mucin-type transmembrane glycoprotein that can regulate the function of immune cells and is related to the malignant progression of several tumor types, but the association between PDPN and the microbiota is still unclear." (PMID 40693815, 2025). "Moreover, in patients with higher tumor burden, circulating or tissue-associated podoplanin may form complexes with CLEC-2 that sterically hinder antibody recognition in sandwich ELISA assays." (PMID 41209555, 2025). "As PDPN has furthermore been identified as an inhibitory surface protein on T-cells in a tumor setting, we questioned whether PDPN might have an immune regulatory function in tumor-associated myeloid cells as well." (PMID 30972297, 2019). "Therefore, the podoplanin-CLEC-2 axis may play an important role in platelet aggregation induced by tumor cells and, consequently, in the cancer-associated thrombosis." (PMID 31337034, 2019). "In addition to its role in tumor cells, PDPN also plays a role in cancer-associated fibroblasts." (PMID 31321241, 2019). "Our findings suggested that LSCC-associated podoplanin was functional and could attenuate the potential for lymph node metastasis, possibly based on the suppression of tumor lymphangiogenesis; thus, podoplanin in cancer cells may become a useful biomarker to measure the malignancy of lung SCC." (PMID 21034514, 2010). "PDPN expressions are regulated by several tumor-promoting pathways, including 12-O-tetradecanoylphorbol-13-acetate (TPA), rat sarcoma viral oncogene homolog (RAS), and the proto-oncogene tyrosine-protein kinase Src (SRC)." (PMID 41594182, 2026). "PDPN promotes tumor cell migration and invasion by regulating cytoskeletal remodeling and Rho GTPase-dependent signaling pathways, and through its interaction with CLEC-2 contributes to tumor–stromal crosstalk and metastatic potential." (PMID 41594182, 2026). "Podoplanin: Podoplanin is a transmembrane glycoprotein involved in cell differentiation, immune response modulation, and tumor progression." (PMID 41438588, 2026). "To resolve the lymphatic microvascular response from that of the CD31+ microvasculature in SA-HFIRE, we analyzed podoplanin (PDPN), a lymphatic-specific glycoprotein, within the viable tumor region and the peritumoral fat pad." (PMID 39998766, 2025). "Beyond direct tumor cell functions, PDPN also plays a critical role in shaping the immunosuppressive tumor microenvironment (TME)." (PMID 41573582, 2025). "In the analyzed specimens, membranous PDPN staining was observed across all three tumor types; however, the proportion of stained areas differed between EMPM and NSCLCs." (PMID 40428290, 2025). "This study revealed that PDPN, a transmembrane glycoprotein enriched in CAF, is highly expressed in the TME of CRC and is associated with macrophage infiltration and tumor progression." (PMID 40842027, 2025). "PDPN protein expression on LECs in metastatic LNs was higher than that in distant LNs, indicating that tumor metastasis alters LECs in metastatic LNs." (PMID 41249124, 2025). "Additional context-dependent markers include CD90 (Thy-1), podoplanin (PDPN), and tenascin-C (TNC), which are associated with immune modulation, stromal remodeling, and therapy response in specific tumor types." (PMID 41441395, 2025). "Therapeutic strategies targeting PDPN have shown effects of enhancing anti-tumor immunity and prolonging survival of mice in preclinical models." (PMID 40890855, 2025). "Another population of FAP+PDPN+ CAFs, which closely interacts with T cells at the tumor periphery, was shown to significantly suppress the proliferation of CD4+ and CD8+ T cells by secreting nitric oxide." (PMID 40890855, 2025). "Podoplanin has been identified on several tumor cells and induces platelet aggregation as a ligand of platelet receptor C-type lectin receptor type-2." (PMID 40725619, 2025).